COPE (coat protein complex I subunit epsilon)
Description:
The coatomer is a cytosolic protein complex that binds to dilysine motifs and reversibly associates with Golgi non-clathrin-coated vesicles, which further mediate biosynthetic protein transport from the ER, via the Golgi up to the trans Golgi network. The coatomer complex is required for budding from Golgi membranes, and is essential for the retrograde Golgi-to-ER transport of dilysine-tagged proteins. In mammals, the coatomer can only be recruited by membranes associated with ADP-ribosylation factors (ARFs), which are small GTP-binding proteins; the complex also influences the Golgi structural integrity, as well as the processing, activity, and endocytic recycling of LDL receptors (By similarity).
Synonyms: Epsilon-COP
Tractability: Antibody: UniProt places it where antibodies can reach, with medium confidence. PROTAC: UniProt records ubiquitination sites on it; ubiquitination databases record sites on it; its protein half-life has been measured.
Gene: Protein-coding gene on chromosome 19 (18,899,514 to 18,919,400, reverse strand). Ensembl gene ENSG00000105669.
Subcellular location: Cytoplasm; Golgi apparatus membrane; Cytoplasmic vesicle, COPI-coated vesicle membrane
Subcellular location (Human Protein Atlas): Golgi apparatus
Pathways (Reactome):
Vesicle-mediated transport: COPI-dependent Golgi-to-ER retrograde traffic; COPI-mediated anterograde transport
Gene Ontology:
Molecular function: protein binding; structural molecule activity
Biological process: endoplasmic reticulum to Golgi vesicle-mediated transport; intra-Golgi vesicle-mediated transport; retrograde vesicle-mediated transport, Golgi to endoplasmic reticulum
Cellular component: Golgi apparatus; COPI vesicle coat; cytosol; endoplasmic reticulum membrane; Golgi membrane; transport vesicle; COPI-coated vesicle; COPI-coated vesicle membrane; cytoplasm; cytoplasmic vesicle
Genetic constraint (gnomAD): Loss-of-function variants: 20 observed, 38.02 expected, observed/expected ratio (o/e) 0.53, 90% interval 0.37 to 0.76. The upper end of that interval is the gene's LOEUF score, 0.76, which puts it in group 3 of 6, group 1 being the genes least tolerant of losing a copy. Missense variants: 402 observed, 392.32 expected, observed/expected ratio (o/e) 1.02, 90% interval 0.94 to 1.11. Synonymous variants: 195 observed, 173.73 expected, observed/expected ratio (o/e) 1.12, 90% interval 1 to 1.26.
Homologues: Orthologues: macaque COPE (98% identical), dog COPE (94% identical), pig COPE (93% identical), chimpanzee COPE (90% identical), mouse Cope (90% identical), guinea pig COPE (89% identical), tropical clawed frog cope (77% identical), zebrafish cope (76% identical), rat Cope (64% identical), Drosophila melanogaster epsilonCOP (37% identical), Caenorhabditis elegans cope-1 (35% identical).
Diseases named in the same sentence as COPE in open-access papers:
COPE is named in the same sentence as 6 diseases in open-access papers, as found by Europe PMC text mining. Sharing a sentence is not in itself a finding about the gene and the disease. The quoted sentences say what the papers report.
obstructive sleep apnea (2 papers, 2018 to 2020). "Circulating anti-COPE (coatomer protein complex subunit epsilon) has been identified as a potential marker for cardiovascular and cerebrovascular events in patients with obstructive sleep apnea." (PMID 32973414, 2020). "Elevated levels of antibodies against coatomer protein complex subunit epsilon (COPE) and DAN family BMP antagonist (NBL1) have been suggested to contribute to a high risk of cardiovascular events in patients with obstructive sleep apnea." (PMID 30479572, 2018).
atherosclerosis (1 paper, 2021). A disease characterized by the build-up of fatty material and calcium deposition in the arterial wall resulting in partial or complete occlusion of the arterial lumen. "Serum anti-COPE was identified by SEREX screening using serum samples from patients with atherosclerosis, and its level was elevated in patients with OSA compared with in HDs." (PMID 34103026, 2021).
cervical cancer (1 paper, 2020). A primary or metastatic malignant neoplasm involving the cervix. "Three genes (COPE, RAB3B, and TFPI) in the network were significantly associated with overall survival (P < 0.05), which indicated that these genes could act as prognostic biomarkers for patients with cervical cancer." (PMID 33330502, 2020). "Analysis of a TCGA dataset revealed that a total of 3 target genes (COPE, RAB3B, and TFPI) in the regulatory network were correlated to survival curves with clinically significant outcomes in cervical cancer." (PMID 33330502, 2020).
tumor (2 papers, 2015 to 2020). "For COPE a slight increase in the protein expression levels in tumor cells, except KAT-18, with respect to Nthy-ori 3–1 was observed." (PMID 26431489, 2015). "Similarly, only EVs released by hypoxic tumours were found to contain the ‘coatomer’ complex of subunits alpha (COPA), beta (COPB1), and epsilon (COPE), which mediate protein cargo transport between the Golgi and endoplasmic reticulum." (PMID 33050615, 2020).
infection (1 paper, 2018). The state of being infected such as from the introduction of a foreign agent such as serum, vaccine, antigenic substance or organism. "Interestingly, COPE also appears to be downregulated during early infection in ‘bystander’ cells; i.e. cells that originate from an infected culture but are themselves not infected." (PMID 29451494, 2018).
COPE also shares sentences with these, for which no sentence is quoted: hepatocellular carcinoma (1 paper).